MIR5010 (microRNA 5010)
Synonyms: hsa-mir-5010; mir-5010
Gene: MicroRNA gene on chromosome 17 (42,514,188 to 42,514,307, forward strand). Ensembl gene ENSG00000283929.
Homologues: Orthologues: chimpanzee MIR5010 (100% identical).